RNU6-622P (RNA, U6 small nuclear 622, pseudogene)
Gene: Small nuclear RNA gene on chromosome 1 (75,183,045 to 75,183,147, forward strand). Ensembl gene ENSG00000206999.
Homologues: Orthologues: chimpanzee U6 (98% identical), macaque U6 (94% identical), guinea pig U6 (89% identical), dog U6 (83% identical), pig U6 (76% identical). Paralogues in human: RNU6-140P (86% identical), RNU6-333P (86% identical), RNU6-144P (85% identical), RNU6-20P (85% identical), RNU6-211P (85% identical), RNU6-35P (85% identical), RNU6-836P (85% identical), RNU6-961P (85% identical), RNU6-1029P (84% identical), RNU6-1036P (84% identical), RNU6-128P (84% identical), RNU6-1316P (84% identical), and 1289 more.